IL6 (interleukin 6)
Diseases named in the same sentence as IL6 in open-access papers (continued):
Sharing a sentence is not in itself a finding about the gene and the disease.
COVID-19 (continued). "Our results showed that critically ill COVID-19 patients had increased serum levels of IL-1β, IL-1RA, IL-6, IL-9, and CXCL10, and lower levels of IL-2 and IL17A as compared to healthy volunteer donors." (PMID 33995342, 2021). "In the present study, IL-6 levels were significantly higher in severe COVID-19 and active AOSD patients compared with HC, suggesting uncontrolled amplification of cytokine production." (PMID 34367188, 2021). "In an early pandemic, it was reported that IL-6 plays a significant role in the cytokine storm in COVID-19 patients, opening new hopes to treat the cytokine storm by blocking the IL-6 cytokine receptor." (PMID 34220807, 2021). "Administration of this IL-6 inhibitor tocilizumab has been shown to result in improvement of clinical and inflammatory markers within 24 hours of infusion among patients with COVID-19." (PMID 33777563, 2021). "A Norwegian study reported increased IL-6 and MCP-1 were associated with respiratory failure in COVID-19-positive patients." (PMID 34960684, 2021). "Among the overexpressed cytokines and chemokines in COVID-19 patients, IL-6 represents a valuable biomarker due to the correlation of its plasma level observed in critical patients with both viral load and lung injury." (PMID 34209845, 2021). "• IL-6 levels in COVID-19 are elevated early in disease, although lower compared to other cytokine storm states." (PMID 33815405, 2021). "In serum of patients with severe COVID-19, the levels of IL-6, MIG, TNF-α, IL-8, IL-18 and IP-10 were higher than in the healthy controls (–G), while in moderate disease only the levels of IL-18, IL-8 and IP-10 were higher." (PMID 34539644, 2021). "Baricitinib is a selective inhibitor of JAK1 and JAK2 and believed to interfere with the signaling of key cytokines that are produced abundantly in COVID-19, including IL-2, IL-6, IL-7, and granulocyte monocyte colony-stimulating factor." (PMID 34359931, 2021). "The machine learning models significantly outperformed the predictive scores derived from established COVID-19 risk factors such as age, BMI, Charlson comorbidity index (CCI), or molecular predictors such as CRP or IL-6 levels." (PMID 34139154, 2021). "The role of IL-6 in the immunopathogenesis of COVID-19 is supported by extensive research data showing an increase in the concentration of this cytokine in patients’ serum." (PMID 34205217, 2021). "RT-qPCR revealed significantly reduced SOCS3 mRNA in spike S2-expressing cells, implying enhanced IL-6 signaling which is a key part of the cytokine storm occurring in severe COVID-19." (PMID 34073047, 2021). "Active AOSD patients share features of hyperinflammation and cytokine storm with severe COVID-19 patients but possess a distinct cytokine profile, including elevated IL-18, IL-6, IFN-γ, and IL-17A." (PMID 34367188, 2021). "Inhibiting both trans- and classical signaling with marketed IL-6 inhibitors (tocilizumab, siltuximab and sarilumab) in severe COVID-19 patients has been effective in several small studies and case reports thus far." (PMID 33628091, 2021). "More recently, the REMAP-CAP trial has shown the benefit of anti-IL6R therapy when given to critically ill patients on admission to intensive care units, indicating that IL6 does contribute to critical illness from COVID-19." (PMID 33704068, 2021). "A large number of studies have shown that IL-6 can trigger a downstream cytokine storm in patients with COVID-19, resulting in lung damages, aggravating clinical symptoms and developing excessive inflammation and acute respiratory distress syndrome (ARDS)." (PMID 37287491, 2021). "Macrophages were also activated to produce a series of inflammatory factors such as IL-6, IFNγ, IL-2, IP-10, IL-1β, in patients with COVID-19." (PMID 34602072, 2021). "In severe COVID-19 infected individuals, interleukin (IL)-6, IL-10, and TNF-α are significantly higher, and it is known that proinflammatory cytokines and chemokines contribute to the occurrence of ARDS." (PMID 33467466, 2021).
COVID-19 (continued). "It was notable that we failed to observe an obvious elevation of inflammatory monocyte-released IL-6 and IL-1β22, which were reported to be responsible for inducing an inflammatory storm in severe COVID-19 patients." (PMID 34373443, 2021). "Our previous rapid systematic review on observational studies suggested a benefit for IL-6 (receptor) antagonist on mortality for COVID-19 patients." (PMID 34728658, 2021). "The circulating levels of IL-8 and IL-6 are significantly higher in COVID-19 patients admitted to an intensive care unit (ICU) or who died." (PMID 34281182, 2021). "Tocilizumab administration in COVID-19 reduces mortality and speeds up clinical improvement in patients with a baseline concentration of IL-6 > 100 pg/mL, particularly if they need oxygen supplementation owing to the lower value of SpO2 ≤ 90%." (PMID 33918563, 2021). "The downregulation of ACE2 resulted in the upregulation of interleukin 6, one of the pivotal mediators of cytokines storm in severe COVID-19 patients." (PMID 34725366, 2021). "Particularly, circulating IL-6, the central milestone of the cytokine storm, is an independent predictor of lung injury and the severity of pneumonia in COVID-19 patients." (PMID 34356384, 2021). "Meta-analyses of published studies on COVID-19 laboratory findings indicated that serum levels of IL-6 were among the most predictive biomarkers." (PMID 34576169, 2021). "A number of approaches to COVID-19 therapy have been investigated, including chloroquine, antiviral drugs, interleukin-6 pathway inhibitors, and other immunomodulators." (PMID 34208017, 2021). "A clinically relevant aspect of the pandemic COVID-19 is its ability to induce the so-called cytokine storm (CS) that consists of interleukin-1 (IL-1), interleukin-6 (IL-6), interleukin-8 (IL-8), and tumor necrosis factor-alpha (TNF-α)." (PMID 33850936, 2021). "Correspondingly, there are increased serum levels of TNF, IFNG, and IL6 in confirmed COVID-19 patients." (PMID 33737867, 2021). "The serum level of IL-6 is highly predictive of respiratory failure within three days in COVID-19 patients." (PMID 34441262, 2021). "To date, many observational studies on and case reports of COVID-19 patients receiving IL-6 inhibitors, mostly tocilizumab, have demonstrated improved clinical outcomes." (PMID 34959657, 2021). "Consistent with the decrease of IL-6 level in our study, these results suggest that inflammation in patients with COVID-19 were alleviated through the neutralizing SARS-Cov-2 antibodies contained in convalescent plasma." (PMID 33746945, 2021). "The serology profile of patients with severe COVID-19 commonly include elevations in interleukin-6 (IL-6) and cytokine storms." (PMID 33572857, 2021). "Several inflammatory CCs and notably MCP1, IP10, IL6, IL1Ra, IL10 and TNFa had more associations (COVID-19) with the BIMs suggesting that these CCs are the inflammatory markers driving brain injury." (PMID 34838058, 2021). "The revelation of the positive correlation between the systemic IL-33, IL-6, and IL-12 levels in serum of COVID-19 patients suggested the synergistic effect of these cytokines in the pathogenesis of COVID-19 disease." (PMID 34917631, 2021). "Several plasma proinflammatory cytokines including IL-6 were elevated in both mild and severe COVID-19 patients." (PMID 34619366, 2021). "Serologically, the IL-6 level increased in COVID-19 patients as their clinical symptoms worsened, together with the initial indicator of their cytokine-level fluctuations." (PMID 33628506, 2021). "A recent report showed that IL-6 and IL-10 predicted COVID-19 severity confirmed by a ROC analysis (AUC = 0.841 and 0.822, respectively)." (PMID 33668514, 2021). "HLH has been linked to NET induction and production of cytokines such as IL-1β, IL-6, IL-8 and IL-17, elevated in both KD and COVID-19." (PMID 33684134, 2021).
COVID-19 (continued). "Compared to patients with moderate COVID-19, patients with severe/critical infections have much higher levels of inflammatory cytokines, particularly interleukin IL-6, IL-1β, and TNF-α, in their BALF and lung tissue." (PMID 33468250, 2021). "Elevated serum levels of pro-inflammatory cytokines, such as IL-6, IL-8, and tumor necrosis factor α, are observed in immune cells of exacerbated cases of COVID-19." (PMID 34944639, 2021). "Decreased lymphocyte numbers and increased levels of inflammatory mediators, such as hypersensitive C reactive protein (hs-CRP) and interleukin-6 (IL-6) were also reported in COVID-19 patients." (PMID 33811756, 2021). "It has been shown that an increase in the level of cytokines and in particular interleukin-6 is a biomarker of the severe course of COVID-19." (PMID 33920986, 2021). "The main findings of this study are that IL-6 is a potential predictor of COVID-19 severity in patients with obesity, while troponin and LDH can be used as predictive biomarkers of COVID-19 severity in MS patients." (PMID 33809913, 2021). "Among the antiviral activities that melatonin has, by suppressing multiple inflammatory pathways (e.g., IL6 and IL-1β), these effects are directly relevant given the well-described pulmonary pathophysiological characteristics of patients with severe COVID-19." (PMID 35723382, 2021). "Principal component and network analyses demonstrated central roles for IL-6 and GM-CSF in COVID-19 pathogenesis." (PMID 33692097, 2021). "Recent data have shown that minocycline is an effective drug, being able to reduce COVID-19–related complications through attenuation of cytokine storm as apparent by the reduction of IL-6, IL-1, and TNF-α." (PMID 33967777, 2021). "It has been shown that even if blood IL-6 levels were elevated in patients with COVID-19, they were lower than the values typically reported in acute respiratory distress syndrome." (PMID 33804100, 2021). "Much is already known of the role of IL-6 in COVID-19, and its involvement with the pathogenesis of cytokine storm, and disease severity." (PMID 35095519, 2021). "Three important cytokines involved in these processes are TNF-α, IL-1, and IL-6, which were increased in COVID-19." (PMID 34177896, 2021). "Namely, the four main cytokines/chemokines detected in the blood of COVID-19 patients were analyzed: IL-6, IL-17, TNFα, and GM-CSF." (PMID 34248910, 2021). "Amygdalin is a candidate compound for COVID-19 treatment by regulating IL6, SRC, MAPK1 EGFR and VEGFA to involve in PI3K-Akt signalling pathway, VEGF signalling pathway and MAPK signalling pathway." (PMID 34908920, 2021). "Obesity is characterized by a chronic low state of inflammation and cytokines produced in adipose tissue (TNF-α, IL1β, IL-6 and IL-15) are similar to those involved in COVID-19." (PMID 33890193, 2021). "It appears that IL-6 is one of the key factors in the onset and progression of cytokine storm in COVID-19 patients." (PMID 34684094, 2021). "The levels of pro-inflammatory cytokines were significantly higher in the patients with COVID-19 when compared to the healthy control group (Unpaired T-test, p = 0.0001 for IL-1β and p = 0.0003 for IL-6)." (PMID 34443474, 2021). "Patients with COVID-19 showed high mRNA expression and secretion of cytokines, IL-1β, IL-6, TNF-α, and IL-18, but showed a significant reduction in IL-6 and IL-1β after treatment with nanocurcumin." (PMID 34025433, 2021). "Clinical trials in multiple countries are currently ongoing to examine the use of the IL-6 inhibitors tocilizumab, siltuximab, and sarilumab in COVID-19 patients." (PMID 33714258, 2021). "The occurrence of hyperinflammation, illustrated by enhancing levels of IL-6, IL-8, and sRAGE, explains the biphasic pattern in COVID-19, with an early viral replication phase, followed by a hyper-inflammatory phase involving cytokine release." (PMID 34000622, 2021).
COVID-19 (continued). "COVID-19 being an infection triggers the inflammatory cascade and cytokines such as IL-6, IL-17, and TH-17, leading to SIRS, ARDS, and multiorgan failure." (PMID 34055545, 2021). "One of the most important cytokines in COVID-19 is pro-inflammatory interleukin-6 (IL-6), whose serum level strongly correlates with the severity of the disease." (PMID 33920709, 2021). "Several studies have been published to date that identify clinical features in severe COVID-19 patients such as elevated IL-2, IL-6, TNF-α and IFN-γ, that can resemble the cytokine profile seen in HLH." (PMID 33803997, 2021). "Increased serum IL-6 levels have been reported in COVID-19 patients, correlating with the severity of COVID-19 pneumonia and mortality risk, or respiratory failure and the need for mechanical ventilation." (PMID 34576169, 2021). "Elevated levels of inflammation-related cytokines, including IL-6, IL-8, and IL-10 were found in patients with COVID-19." (PMID 34031269, 2021). "Chemokines such as IL-8/CXCL8 and proinflammatory cytokines such as IL-6 (p<0.05) and TNFα (p<0.05) were increased 1.4-, 4.7-, and 1.3-fold, respectively, in the plasma of patients with critical COVID-19, in comparison with patients with mild disease." (PMID 34122423, 2021). "The high surge of IL6, IL1b, IFNγ, C-reactive protein, and TNF-α senescence leads to lower airway and lung injury and increased risk for COVID-19 in elderly patients." (PMID 33815889, 2021). "The linear multiple regression model was calculated to predict the levels of IL-33 based on COVID-19 severity, IL-6, IL-1β, IL-12, TNF-α, and IL-23." (PMID 34917631, 2021). "Elevated serum C-reactive protein (CRP), a protein whose expression is driven by IL-6, is also a biomarker of severe clinical manifestations of COVID-19." (PMID 34185801, 2021). "In several studies, it was found that the interleukin 6 (IL-6) level was elevated in the COVID-19 patients' serum and this was related to the severity of the disease." (PMID 34306612, 2021). "ATX levels in severe COVID-19 patients correlated with the increased IL-6 serum levels, as recently also shown in ARDS, as well in acute-on-chronic liver failure (ACLF) patients, suggesting interdependent regulation of expression." (PMID 34671341, 2021). "The standard cutoff thresholds for IL-6 concentration in blood plasma for confirming a severe course of COVID-19 and serious sepsis vary from 20 to 450 pg/mL, with a norm of IL-6 of 5–7 pg/mL." (PMID 34299201, 2021). "Other sulphur-containing compounds such as cysteine and taurine have been found to be reduced in COVID-19 cases compared to controls, and in COVID-19 patients with moderate-high IL-6 levels." (PMID 34928464, 2021). "Some studies have suggested that the dynamic change of IL-6 and IL-1 levels and other cytokines can be used as a marker in disease monitoring in patients with severe COVID-19." (PMID 33747583, 2021). "Elevated levels of interleukin-6 and hyperferritinemia should be considered as red flags of systemic inflammation and poor prognosis in COVID-19." (PMID 34185801, 2021). "The common profile of a COVID-19 patient with cytokine storm syndrome includes elevated interleukin-6 (IL-6), IL-2 receptor, TNF-α, granulocyte-colony stimulating factor, among others." (PMID 34124207, 2021). "Disease severity and death of COVID-19 patients have been correlated to the elevated expression of IL-6 and TNFα." (PMID 34866574, 2021). "A prognostic nomogram based on IL-6 highlights the key role of cytokines in COVID-19 pathophysiology." (PMID 33693017, 2021). "First, decreased hepatic albumin production is associated with increased release of proinflammatory mediators belonging to the COVID-19-related cytokine storm, such as IL-6 and tumor necrosis factor-alpha (TNF-alpha)." (PMID 34683480, 2021).
COVID-19 (continued). "In a recent study from the Netherlands, the authors showed that IL-6 values were lower in patients with COVID-19 and acute respiratory distress syndrome (ARDS) when compared to patients with septic shock with ARDS or septic shock without ARDS." (PMID 33815405, 2021). "Elevated plasma IL-6 levels were observed in three-quarters of severe COVID-19 patients and in only one-third of mild cases." (PMID 34300181, 2021). "Altogether, these data suggest that the severity of COVID-19 may be associated with inflammasome activation in monocytes that results in large amounts of IL-1ß and generates an excessive inflammatory response, further characterized by high levels of IL-6 and TNF-α." (PMID 33649297, 2021). "Tocilizumab, an anti-IL6 medication, was tried on COVID-19 patients but was shown to be ineffective in a randomized controlled trial." (PMID 35145507, 2021). "Cytokine response in severe COVID-19 patients was clearly marked by elevated levels of pro-inflammatory cytokines, including IL-6, IL-8, MCP-1, and IL-18 compared to healthy donors." (PMID 33692788, 2021). "Amongst these, the most studied one is IL-6, which is increased both in mild and severe COVID-19 patients and correlated with the pulmonary infiltration area in patients with ARDS." (PMID 34073872, 2021). "Since IL-6 levels are important indicators for the severity of COVID-19, we examined Aβ1-42-mediated changes in IL-6 production in A549 cells, an immortalized human alveolar epithelial cell line." (PMID 34360989, 2021). "Tocilizumab, a monoclonal anti-IL-6 antibody, is a promising anti-inflammatory regent in the treatment of COVID-19 but the results are mixed results from clinical trials." (PMID 34055887, 2021). "This is not surprising because HNE can act as a signaling molecule suppressing IL-6 production, but it is worth mentioning that it was only transient and was only observed for the patients who eventually died from COVID-19." (PMID 34572973, 2021). "Our study also demonstrated that CRP and IL-6 levels were higher in the critical COVID-19 group and correlated positively with NHR." (PMID 34589058, 2021). "In severe COVID-19 lung macrophages displayed high expression of IL-1β, IL-6, TNF-α and various chemokines (CCL2, CCL3, CCL4, CCL7, CXCL9, CXCL10 and CXCL11)." (PMID 34054832, 2021). "The results of inhibiting both trans- and classical- signaling with marketed IL-6 inhibitors (tocilizumab, siltuximab and sarilumab) in severe COVID-19 patients are effective based on several small studies and case reports thus far." (PMID 33628091, 2021). "In a cohort study including 452 patients in Wuhan, China, an increase of interleukins IL-2, IL-6, IL-8, IL-10, and NF-κβ was observed in COVID-19-infected patients." (PMID 33969006, 2021). "Seventy-five percent of patients with COVID-19 had thyroid abnormalities and higher IL-6 levels (76.10 ± 82.35 vs. 6.99 ± 3.99, 95% CI 52.18–100.01, P-value <0.01)." (PMID 33784355, 2021). "The levels of IFN-γ, IL-4, IL-6, and IL-12 were significantly higher in colostrum obtained from those participants who exhibited COVID-19-related symptoms." (PMID 34382820, 2021). "The coagulation function-related indicator D-dimer had a significant positive correlation with CRP and IL-6 in COVID-19 patients." (PMID 34222271, 2021). "A recent meta-analysis reported an overall effect in favor of the use of anti-IL-6 for the control of COVID-19." (PMID 34421600, 2021). "With regard to treating COVID-19, an observational study revealed the improvement of outcomes in most patients after receiving siltuximab, as demonstrated by a decrease in IL-6 and CRP levels." (PMID 34001144, 2021). "Combining SpO2/FiO2 with high IL-6 and SARS-CoV-2 RNAaemia which reflect hyperinflammation and viral overload allows accurately and before intubation identifying COVID-19 patients at high risk for ECMO use or in-hospital death despite the use of MV." (PMID 34379684, 2021).